DES (desmin)
Diseases named in the same sentence as DES in open-access papers (continued):
Sharing a sentence is not in itself a finding about the gene and the disease.
liver fibrosis (39 papers, 2010 to 2025). "As only some HSCs express mGFP and HSCs are the main cause of liver fibrosis, we want to know the difference between Desmin+ HSCs and mGFP+ HSCs (Reelin‐expressing HSCs and their progeny) in fibrotic livers." (PMID 37246473, 2023). "Biomarkers of liver fibrosis, such as FN, Collagen I, desmin, and α‐SMA, were detected, and 10 mg·kg−1 Ssb1 exerted a considerable effect on fibrosis alleviation; which had about the same efficacy as the commercial inhibitor S3I‐201." (PMID 41163803, 2025). "Given that desmin is a universal marker for HSCs10, these results indicate that CflarLKO mice rapidly developed severe liver fibrosis along with an increase in the number of HSCs after being fed the CDE diet." (PMID 37813881, 2023). "The activation and proliferation of stellate cells play a major role in the pathogenesis of hepatic fibrosis, and activated stellate cells up‐regulate the expression of desmin." (PMID 35869934, 2022). "Liver fibrosis was assessed by Picro-Sirius-Red, desmin staining and hepatic hydroxyproline content." (PMID 33435509, 2021). "Desmin, a protein produced by activated HSCs, which is strongly upregulated in liver fibrosis was threefold to fourfold higher at 18‐ and 24‐month relative to 7‐ or 12‐month." (PMID 34761505, 2021). "Immunochemical staining exhibited that the α-SMA and DESMIN increased with liver fibrosis progression and other fibrosis-related genes were also remarkably enhanced." (PMID 32117757, 2020). "Group 3 (MPOE-treated) showed a significant reduction of α-SMA and desmin protein expression compared to the liver fibrosis control group." (PMID 29849890, 2018). "α-SMA and desmin protein expression were significantly elevated in liver fibrosis control group than in the normal control." (PMID 29849890, 2018). "Here, in rat and mouse models of liver fibrosis, nuclear Sox9 localized to desmin-positive cells, confirming its presence in HSCs." (PMID 22488688, 2012). "Similarly, the expressions of the genesCOL1A1,COL3A1,ACTA2,DES,TGFβ1, andVIM, which are involved in liver fibrosis, increased in liver organoids treated with 100 mM and 200 mM ethanol." (PMID 38818583, 2024). "Moreover, Sirius red staining and desmin immunostaining (representing activated fibroblasts) revealed that βCD-PRX effectively suppressed liver fibrosis." (PMID 37725372, 2023). "In situ hybridization assays using fibrotic mouse livers showed that Dbn1 mRNA was present in Desmin-positive cells, indicating that drebrin was expressed in activated hepatic stellate cells (HSCs), which are the main collagen-producing cells in hepatic fibrosis." (PMID 36690273, 2023). "HJRG and silymarin can reduce the desmin and vimentin content of liver fibrosis rats (p < 0.05)." (PMID 35942372, 2022). "Liver fibrosis monitored by the accumulation of α-Sma, collagen I, desmin, and Sirius red staining, as well as by measuring the mRNA levels of α-Sma, Col1a1, Mmp-3, and Tgfβ1, was significantly decreased by KY19334 treatment compared to treatment with selonsertib or ocaliva." (PMID 36114279, 2022). "Genes known to be upregulated in cholestasis-induced hepatic fibrosis, including desmin and αSMA markers of HSC, as well as structural proteins of extracellular matrix (ECM) such as collagen types I and III, and integrins, were tested in Mdr2KO mice and FVBN controls treated with vehicle, DG or Ghr." (PMID 32994489, 2020). "Furthermore, MPOE ameliorated liver fibrosis as evidenced by the reduced expression of desmin, α-smooth muscle actin (α-SMA), transforming growth factor-β1 (TGF-β1), and SMAD3 proteins." (PMID 29849890, 2018). "The results showed that the collagen deposition and liver fibrosis caused by S. japonicum infection were markedly alleviated after DKK1 treatment, which was accompanied by a decrease in the expression of α-SMA/Acta2, desmin and Col1a1." (PMID 28331224, 2017).
liver fibrosis (continued). "Finally, in LE rats, chronic ethanol exposure significantly increased expression of ABST, GFAP, desmin, and collagen, indicating that bile duct epithelium and stellate cells were more activated, and that genes responsible for hepatic fibrosis, that is, desmin and collagen, were up-regulated." (PMID 20814553, 2010). "Activated HSCs play a key role in the initiation and development of liver fibrosis and express markers such as α-SMA and desmin." (PMID 40524220, 2025). "Masson's staining and the expression of desmin and αSMA confirmed that the inhibition of BMP signalling led to more severe liver fibrosis." (PMID 38623945, 2024). "Histologically, reversine significantly decreased the expression of the liver fibrosis markers α‐SMA and Desmin, and decreased the expression of biliary protein markers CK7, CK19, and EpCAM, demonstrating reversine's ability to attenuate DR and fibrogenesis." (PMID 36929584, 2023). "The inhibitory effect of α-mangostin on liver fibrosis markers was also demonstrated by the mRNA levels of α-SMA, col1a2, MMP2 and desmin." (PMID 37760177, 2023). "We also assessed two markers of liver fibrosis, α‐SMA, and Desmin, via immunostaining in liver tissues." (PMID 36929584, 2023). "In both the CCl4-induced rat and mouse liver fibrosis experiments, IHC staining showed that high a-SMA and desmin was expressed in the fibrotic septum in the CCl4 group." (PMID 34630075, 2021). "Next, α-SMA and desmin staining, the components of the HSC cytoskeleton, indicated that miR-98 overexpression attenuated hepatic fibrosis in vivo." (PMID 32637414, 2020). "In the liver fibrosis control group, α-SMA staining located in the myofibroblast cells along collagenous septa bridging portal areas and central areas and desmin immunostaining was observed in perisinusoidal cells and interstitial myofibroblasts." (PMID 29849890, 2018). "The results of immunohistochemical staining showed that QG reduced the number of α-SMA- and desmin-positive cells in the liver tissues of CCl4- and HFHCD-induced liver fibrosis mice, suggesting that QG could inhibit the activation of HSCs." (PMID 40524220, 2025). "Similarly, as important fibrotic markers, α-SMA, TGF-β, COL1A1, and desmin expression was also inhibited by KXRG treatment, thus inhibiting hepatic fibrosis." (PMID 34422075, 2021). "The CCl4-induced liver fibrosis mouse model showed that the administration of α-mangostin significantly decreased the expression of the fibrosis markers (α-SMA, collagen-a2 (col1a2), desmin and matrix metalloproteinase-2 (MMP-2)) as well as attenuated hepatic collagen deposition and liver damage." (PMID 37760177, 2023). "The expression of α-SMA, a typical marker of activated HSCs, and desmin, an indicator of intermediately differentiated HSC/MFB, was assessed by immunohistochemistry to evaluate the effect of vaccination with the TGF-β1 kinoids on HSC activation during hepatic fibrosis." (PMID 24349218, 2013). "However, as the model of HCD-induced NASH in mice displays extensive liver fibrosis, the majority of HSCs have likely acquired an activated state; hence, our co-staining of liver sections for VCAM-1 and the pan-HSC marker desmin suggests the presence of VCAM-1 on activated HSCs." (PMID 36902241, 2023). "Immunohistochemical analyses of murine liver fibrosis models revealed that OPN was expressed predominantly in αSMA+ myofibroblasts, but not in desmin+ quiescent HSCs." (PMID 40678531, 2025).
heart failure (38 papers, 2013 to 2025). Inability of the heart to pump blood at an adequate rate to meet tissue metabolic requirements. "Heart failure is accompanied by changes in the cardiomyocyte structure, the loss of cross-striation, and the disorganisation of desmin filaments." (PMID 40564271, 2025). "Mutated desmin or desmin deficiency has been linked to cardiac contractile dysfunction and impaired myocardial metabolism, which is a major reason for heart failure." (PMID 37108147, 2023). "Desmin-deficient mice develop altered muscle architecture, disorganized muscle fibers, skeletal and smooth muscle lesions, cardiac hypertrophy, and heart failure." (PMID 37760006, 2023). "Further, an association between the increase in cleaved desmin and the formation of preamyloid oligomers was reported in both human and murine models of heart failure." (PMID 35625721, 2022). "In the course of heart failure, the structure of the cardiomyocyte is compromised and there is a disorganisation of desmin filaments and loss of cross striation." (PMID 27980728, 2016). "The roles of cytoskeletal alterations especially of microtubules, formed by polymerization of α- and β-tubulin, and desmin have been implicated in the development of cardiac hypertrophy and heart failure in numerous experimental studies." (PMID 27991560, 2016). "The accumulation of cleaved and misfolded desmin is a cellular hallmark of heart failure (HF)." (PMID 32093415, 2020). "With heart failure, the structure of cardiomyocytes and intercalated disks undergoes disorganisation, which leads to loss of myofilaments and their supporting proteins, e.g. desmin." (PMID 27980728, 2016). "In human and canine DCM-related heart failure and in canine ischemia-related progressive heart failure, the structure of cardiomyocytes and intercalated discs undergo structural disorganisation, leading to the loss of myofilaments and their supporting proteins, such as desmin." (PMID 40564271, 2025). "Alterations in the cytoskeleton, particularly changes in microtubules and desmin, play a significant role in cardiac hypertrophy and heart failure." (PMID 40406620, 2025). "Cytoskeletal remodeling, including microtubule densification and desmin aggregation, is a known feature of heart failure that disrupts sarcomere function, leading to reduced contractility and an increased likelihood of heart failure." (PMID 40607964, 2025). "Recent studies demonstrated that Desmin gene expression levels increase in different models of heart failure, as a compensatory mechanism for its augmented misfolding and degradation." (PMID 36902375, 2023). "For instance, in heart failure, desmin filament breakdown precedes mitochondrial dysfunction and oxidative stress, which have important pathophysiological consequences." (PMID 37760006, 2023). "iNOS is colocalized with desmin after human heart failure and inhibition of elevated mTORC1 expression with rapamycin decreasing the number of myocytes with abnormal desmin." (PMID 35625721, 2022). "The mutations of various genes encoding the proteins around the Z-disc, such as ANKRD1, DES, FLNC and CSRP3, are known to cause abnormal responses to mechanical stress, resulting in heart failure." (PMID 39195917, 2022). "Desmin has potential as a novel therapeutic target for heart failure, which needs to be further investigated in more animal models and patient biopsies." (PMID 34285704, 2021). "Rats subjected to aortocaval fistula (ACF), a condition that ultimately leads to heart failure, exhibited perturbations to desmin filament alignment at the Z-bands, and disorganized mitochondria." (PMID 33467597, 2021). "Mice with cardiac overexpression of the misfolded proteins, mutant crystallin B (CryABR120G) and mutant desmin (D7-Desmin), exhibit cardiac dysfunction, heart failure and premature lethality, and thus represent a bona fide mouse model of cardiac proteinopathy." (PMID 33391028, 2020).
heart failure (continued). "Mutations in the human desmin gene (DES) cause autosomal-dominant and -recessive cardiomyopathies, leading to heart failure, arrhythmias, and AV blocks." (PMID 32126091, 2020). "During heart failure, the pattern of desmin, vimentin, periostin and caspase-3 expression alters in the left atrium, regardless of the cause." (PMID 27980728, 2016). "Desmin is one of the critical cytoskeleton proteins of cardiomyocytes that will increase due to the myocardial hypertrophy in patients with heart failure." (PMID 24738046, 2014). "Heart failure is characterized by extensive remodeling of the cytoskeletal architecture, which includes an increase in the density of key cytoskeletal proteins such as desmin, tubulin, and actin." (PMID 40607964, 2025). "Interestingly, tubulin and desmin protein content has been shown to correlate well with left ventricular end-diastolic pressure (LVEDP) in heart failure." (PMID 33732734, 2021). "Cytoskeletal proteins like tubulin and desmin are known to be elevated in heart failure." (PMID 33732734, 2021). "Desmin has potential as a novel therapeutic target for heart failure." (PMID 34285704, 2021). "In this rat model, decreased desmin level correlated with echocardiographic signs of LV hypertrophy, such as increased wall thickness, decreased LV dimensions, and increased fractional shortening, which indicated heart failure." (PMID 34285704, 2021). "Desmin has proven to be a sensitive biomarker for evaluating the deterioration degree of myocardial infarction and it was designated as an intracellular marker for heart failure." (PMID 25889944, 2015). "It has been suggested that desmin may act as an intracellular marker in heart failure." (PMID 29340527, 2018). "Beyond the observed alterations in cellular structure and mitochondria, the mechanisms linking rare genetic mutations to the development of heart failure in patients affected by desmin mutations remain unclear due in part, to the lack of relevant human cardiomyocyte models." (PMID 38167524, 2024). "Up-regulated differentially expressed genes (DEGs) of different datasets showed that the heart failure groups expressed significantly genes involved in cardiac fibrosis, including POSTN and DES." (PMID 36805782, 2023). "Furthermore, in ACF rat model, there was an increase in desmin phosphorylation and accumulation of desmin cleavage products in cardiac muscle, suggesting that cytoskeletal cleavage and breakdown might contribute to the progression of heart failure." (PMID 33467597, 2021). "Integrating the results of the TBX5-targeted genes and the DEGs in toxicity pathways, we found that the dysregulation of TBX5-targeted genes, TNNT2, NPPA, TTN, ATP2A2, DES and SCN5A, contributed to the development of heart failure and arrhythmia." (PMID 32423033, 2020). "In our study, inhibition of TBX5 was shown to dysregulate several genes such as DES, NKX2-5, ACTC1, MYH6, ATP2A2 and HSPB7, which further contributed to ICM-related diseases such as failure of heart and degeneration of heart." (PMID 32423033, 2020). "In a heart-failure mouse model, desmin was cleaved by caspase-6, losing its mechanical and nonmechanical properties and forming cytoplasmic aggregates." (PMID 39195218, 2024). "The lack of desmin in human hearts triggers a cascade of noxious cellular effects often leading to progressive heart failure during adolescence or early adulthood." (PMID 36233322, 2022). "The desmin content in cardiomyocytes directly affects the long-term prognosis of patients with heart failure, and lack of desmin leads to myocyte contractile dysfunction." (PMID 34285704, 2021). "Overall, BubR1 insufficiency appears to drive cardiac phenotypes, including hypertrophy, elevated expression of the heart failure marker Nppa, and increased cytoskeletal proteins such as desmin, which may be independent of its effects on senescence." (PMID 40607964, 2025).
schwannoma (36 papers, 2008 to 2026). A benign, usually encapsulated slow growing tumor composed of Schwann cells. "In fact, the differential diagnosis between schwannoma and our case is extremely difficult in aspect of morphologic features; however, the positive findings of ER, desmin, and CD34, with heterogenous loss of Rb1, in IHC contributed to the accurate diagnosis." (PMID 39493459, 2024). "Immunohistochemical markers including CD117, CD56, CD34, S100, SOX10, Calretinin, Desmin, Vimentin, EMA and smooth muscle antigen are associated with Schwannomas and can be used to confirm their diagnosis." (PMID 39558963, 2024). "Schwannomas and other peripheral nerve sheath tumors usually show S-100/SOX10 positivity, whereas smooth muscle tumors demonstrate desmin and/or α-SMA positivity." (PMID 41431481, 2025). "Schwannomas present negativity for SMA, Desmin, CD34, CD117 and positivity for S-100 protein and NSE." (PMID 30710876, 2019). "In our analysis, we observed that the markers SMA, Desmin, CD117, DOG-1, ALK, Synaptophysin, Chromogranin and AE1/AE3 stained negatively in all analyzed schwannomas." (PMID 30710876, 2019). "In fact, the coexistence of desmin and SMA strongly supported the smooth muscle nature of the observed esophageal neoplastic lesions, while the constant negativity for CD34, CD117 and S-100 excluded other diagnostic hypotheses, including inflammatory fibroid polyps, GISTs and schwannomas." (PMID 24959231, 2014). "The pathological diagnosis was Schwannoma and immunohistochemical testing showed Vimentin (+), S-100 (+), MBP (+), CD56 (+), GFAP (+), Ki-67 (+), Desmin (−), SMA (−), EMA (−), CD34 (positive in tumor vessels)." (PMID 23432938, 2013). "Immunohistochemistry was positive for SOX10 and negative for CD34, DOG1, and desmin, confirming schwannoma." (PMID 41230329, 2025). "Additionally, negative staining for specific protein markers can differentiate schwannomas from the more common lesions, notably CD117 (c-kit) and DOG1 in GIST, and desmin and SMA in smooth muscle tumors." (PMID 38800239, 2024). "Schwannomas test positive for S-100 protein and negative for desmin, smooth muscle actin, CD34, and CD117." (PMID 34410526, 2021). "EUS-FNA was performed and spindle-shaped cells that were immunopositive for S-100 and negative for c-kit, CD34, and desmin were detected, resulting in a diagnosis of schwannoma." (PMID 30631851, 2018). "Similar to all schwannomas, the tumor cells of plexiform schwannoma are uniformly positive for S-100 on immunohistochemistry, while they are negative for c-kit, smooth muscle actin, and desmin." (PMID 34453629, 2021). "Variable yet frequent expression of h-caldesmon and desmin further supports the myoid lineage, whereas negative staining for markers such as S100, CD34, and CD31 rules out schwannomas, solitary fibrous tumors, and vascular endothelial lesions, respectively." (PMID 40507464, 2025). "CD34, C-kit, CAM5.2, desmin, and progesterone receptor were negative, however, cytopathology showed scattered fragments of spindled cells positive for SOX10, consistent with a schwannoma." (PMID 39735038, 2024). "Schwannomas are uniformly positive for S-100, occasionally positive for CD34, and negative for CD117, desmin, and SMA." (PMID 32685549, 2020). "The parameters of schwannoma immunohistochemistry are based on positivity for S-100 protein and on the absence of staining for CD117, CD34, Desmin and specific muscle actin." (PMID 30710876, 2019). "This difference in immunophenotype is represented by the spindle cells of schwannomas showing strong diffuse positivity for S100 and an absence of staining for CD117, DOG1, CD34, desmin, SMA and actin." (PMID 25667620, 2015). "In contrast to GISTs, schwannomas are consistently negative for CD117 (KIT) and usually negative for CD34, CKs, smooth muscle actin and desmin, but strongly positive for S100 protein and vimentin." (PMID 25360169, 2014).
schwannoma (continued). "The diagnosis of schwannoma is based on positive immunohistochemical staining for S-100 protein and negative results for CD117, CD34, desmin, and smooth muscle actin (SMA), whereas GIST is typically positive for CD117, DOG-1, and CD34 but negative for S-100 protein." (PMID 26559271, 2015).